SREBF1 (sterol regulatory element binding transcription factor 1)
Diseases named in the same sentence as SREBF1 in open-access papers (continued):
Sharing a sentence is not in itself a finding about the gene and the disease.
prediabetes (2 papers, 2020 to 2024). "The association of NR1H3 (encoding LXRα) and lipogenic LXR target genes, e.g., SREBF1 (encoding SREBP1, a lipogenic transcription factor), with incident prediabetes/T2D was not significant." (PMID 38747290, 2024).
ZIKV infection (2 papers, 2022 to 2023). "ZIKV infection of moDCs was inhibited by knockdown of SREBF2, but not SREBF1, at least at the knockdown efficiencies achieved here, which suggests that DMHCA blocks ZIKV in part by inhibiting SREBP2 activation." (PMID 36097162, 2022).
Abdominal obesity (1 paper, 2022). Excessive fat around the stomach and abdomen. "Recent studies demonstrated that the methylation of ABCG1, CPT1A, and SREBF1 genes was associated with some cardio-metabolic risk factors including total cholesterol and insulin levels, as well as anthropometric indices of general and abdominal obesity." (PMID 35551677, 2022).
alcoholic hepatitis (1 paper, 2025). Acute hepatitis resulting from ingestion of alcohol. "STAT3, a transcription factor which is activated by a myriad of inflammatory signaling molecules which are abundant in alcoholic hepatitis including IL-6 and IL-10 and in turn binds to the promoter of the SREBF1 gene coding for SREBP-1, leading to its transcription." (PMID 40040391, 2025).
astrocytoma (1 paper, 2023). "These compounds induced SREBF1 but not SREBP1c-mediated lipogenic genes such as SCD1, ACACA and FASN in HepG2 cells or astrocytoma cells." (PMID 36674804, 2023).
autism spectrum disorder (1 paper, 2020). A spectrum of developmental disorders that includes autism, and Asperger syndrome.
autoimmune disease (1 paper, 2025). A disorder resulting from loss of function or tissue destruction of an organ or multiple organs, arising from humoral or cellular immune responses of the individual to their own tissue constituents. "This expanding understanding positions SREBF1 as not only a mediator of lipid homeostasis but also an influencer of autoimmune disease pathophysiology." (PMID 39953634, 2025).
endometritis (1 paper, 2025). An acute or chronic, usually bacterial infectious process affecting the endometrium. "Given that Srebf1 deficiency reduces PUFAs in endometritis tissues and that abnormal PUFA metabolism may contribute to the observed inflammation and placental abnormality and pregnancy loss, we investigated the effects of dietary EPA supplementation." (PMID 40539061, 2025). "Given that CE is a strong risk factor for infertility, recurrent miscarriage and pregnancy complications in humans, we next investigated the impact of endometritis and Srebf1 deletion on fertility." (PMID 40539061, 2025). "Srebf1-/- mice also showed pregnancy loss with placental abnormality without affecting implantation in the endometritis model." (PMID 40539061, 2025). "Given our earlier findings that Srebf1 deletion decreases PUFA levels in skeletal muscle and in macrophages associated with exacerbated inflammation, we speculated that altered fatty acid composition may contribute to the prolonged and exacerbated endometritis observed in Srebf1-/- mice." (PMID 40539061, 2025).
gastroparesis (1 paper, 2019). Paralysis of the muscles of the stomach wall resulting in delayed emptying of the gastric contents into the small intestine. "Several of the predicted PI3K target genes were further examined by qRT-PCR, of these CXCL10 was found to be specifically elevated in high BMI control subjects, whereas HMOX1 and SREBF1 were decreased both in high BMI control subjects and in low BMI subjects with idiopathic gastroparesis." (PMID 31221130, 2019).
Granuloma (1 paper, 2024). A compact, organized collection of mature mononuclear phagocytes, which may be but is not necessarily accompanied by accessory features such as necrosis. "Additionally, spatial transcriptomics and scRNA-seq data of human sarcoidosis lesional and non-lesional skin revealed increased SREBF1 and SREBF2 expression in sarcoidosis granulomas." (PMID 38353578, 2024).
head and neck cancer (1 paper, 2025). A primary or metastatic malignant neoplasm affecting the head and neck. "In head and neck cancers, upregulation of SREBF1, the gene encoding SREBP1, promotes proliferation and migration, and it inhibits apoptosis by upregulating the expression of steroidogenic acute regulatory protein-related lipid transfer 4 (STARD4) and modulating the level of immune cell infiltration." (PMID 40427160, 2025).
hematoma (1 paper, 2025). A hematoma is a collection of blood from a vascular structure into an extravascular space. "In sharp contrast, the uteri of Srebf1-/- mice appeared dark red with accompanying intrauterine fetal death and hematoma formation (red arrowhead)." (PMID 40539061, 2025).
hyperalphalipoproteinemia (1 paper, 2023). An autosomal dominant genetic condition caused by mutation(s) in the CETP gene, encoding cholesteryl ester transfer protein. "A positive contribution of SREBF1 expression up-regulated by liver X receptors assures a supply of fatty acids during sterol overloading at hyperalphalipoproteinemia to allow storage of excess cholesterol as cholesteryl ester." (PMID 37623250, 2023).
Legionella infection (1 paper, 2017). "Legionella infection induced Srebf1 expression as well as SREBP1/2-regulated genes in infected macrophages." (PMID 28357391, 2017).
limb-girdle muscular dystrophy (1 paper, 2017). Limb-girdle muscular dystrophy (LGMD) is a heterogeneous group of muscular dystrophies characterized by proximal weakness affecting the pelvic and shoulder girdles. "Note also the regulatory effects of SREBF1 on remote sites many of which map closely with locations implicated in limb girdle muscular dystrophy." (PMID 28913347, 2017).
Lss (1 paper, 2023). "Transcriptomics studies of the mutant mouse cataract model of Lss, revealed robust increases in the expression levels of genes related to fatty acid metabolism, such as Srebf1 and Scd1, and decreased expression of Srebf1 and Scd1 involved in the cholesterol synthesis pathway." (PMID 37875594, 2023).
Miscarriage (1 paper, 2025). A pregnancy that ends at a stage in which the fetus is incapable of surviving on its own, defined as the spontaneous loss of a fetus before the 22th week of pregnancy. "Dietary supplementation of EPA increased endometrial levels of EPA-containing phospholipids and ameliorated inflammation and miscarriage in Srebf1-/- CE mice." (PMID 40539061, 2025). "Srebf1 deficiency strongly affected fatty acid species, including PUFAs, and EPA supplementation ameliorated inflammation and miscarriage in Srebf1-/- mice." (PMID 40539061, 2025).
myeloma (1 paper, 2025). "To mechanistically confirm that SREBPs inhibition contributes to the anti-myeloma effects of SEL, we performed shRNA-mediated knockdown of SREBF1 and SREBF2 in MM cells, with knockdown efficiency confirmed by immunoblotting." (PMID 40229499, 2025).
osteoporosis (1 paper, 2025). A condition of reduced bone mass, with decreased cortical thickness and a decrease in the number and size of the trabeculae of cancellous bone (but normal chemical composition), resulting in increased fracture incidence. "In addition, our results shown that the upregulation of SREBF1 may pose risks for gastrointestinal dysfunction and osteoporosis, which could be a consideration when targeting SREBF1 for the treatment of CHD and MS in the future." (PMID 39953634, 2025).
parasitemia (1 paper, 2024). "When features were expressed as the Δ, time to parasitemia positively correlated with B cell signatures and “putative SREBF1 targets” but negatively correlated with “chromosome Y-linked” and “Hox cluster I” modules." (PMID 38687615, 2024).
progeria (1 paper, 2023). "Interestingly, progeria‐specific mechanisms in the Aging map, involving SREBF1, GSK3A/B, and FBXW7, are related to PGC1A activity in the PD map, indicating potential cell and tissue specificity of the mechanism." (PMID 36648161, 2023).
sarcoidosis (1 paper, 2024). Sarcoidosis is a multisystemic disorder of unknown cause characterized by the formation of immune granulomas in involved organs. "SREBF1/SREBP1a/c is a transcription factor regulating lipid and fatty acid synthesis, which was predicted to be upregulated in sarcoidosis macrophages by RNA-seq." (PMID 38353578, 2024).
Smith-Magenis syndrome (1 paper, 2011). Smith-Magenis syndrome (SMS) is a complex genetic disorder characterized by variable intellectual deficit, sleep disturbance, craniofacial and skeletal anomalies, psychiatric disorders, and speech and motor delay. "rs11868035 appears in an intron of the alternatively spliced gene, SREBF1 (sterol regulatory element-binding transcription factor 1), within the Smith-Magenis syndrome (SMS) deletion region on 17p11.2." (PMID 21738487, 2011).
thymic lymphomas (1 paper, 2015). "In this study FBXW7 and SREBF1 were negatively correlated consistent with our observation of increased expression of SREBF1 and downstream target genes in thymic lymphomas of FBXW7 heterozygous mice." (PMID 26575021, 2015).
tumor (336 papers, 2006 to 2026). "Mechanistically, SREBF1 is implicated in lipid metabolic reprogramming and interacts with the tumor immune microenvironment, also with genetic alterations." (PMID 40668814, 2025). "CD133 upregulated SEMA3A and SREBF1 by 3- and 5-fold, respectively; these genes have been implicated in the tumor progression of different cancers." (PMID 38727313, 2024). "Sterol regulatory element-binding transcription factor 1 (SREBF1), which encodes for a key transcriptional regulator of lipid metabolism, was also upregulated in tumor tissue." (PMID 33322148, 2020). "For instance, TXNIP amplification may hyperactivate redox-sensitive senescence checkpoints, while SREBF1 loss could disrupt lipid homeostasis, creating a permissive niche for tumor survival." (PMID 40299498, 2025). "SREBF1 has previously been indicated as a hallmark of cancer, and its overexpression has been associated with several mechanisms for tumorigenesis, including the promotion of lipid synthesis, facilitation of tumor survival under stress and dysregulation of cell metabolism." (PMID 40781643, 2025). "In vivo, SF3B4 silencing significantly inhibited tumor growth and reduced SREBF1 expression in xenograft models." (PMID 42255207, 2026). "For instance, miR-29 was found to regulate the sterol regulatory element-binding protein 1 (SREBP1), encoded by the SREBF1 gene, in GBM to inhibit SREBP-dependent cholesterol synthesis and uptake, which limits cell survival and tumor formation." (PMID 41155666, 2025). "In RB, SREBF1 expression was positively related to most tumor biological behaviors such as DNA repair, DNA damage, invasion, apoptosis, and metastasis." (PMID 40668814, 2025). "Focusing on CRC, functional studies revealed that SREBF1 drives tumor progression by enhancing cancer cell proliferation and migration, while its knockdown induces cell cycle arrest and apoptosis in HCT116 cells." (PMID 40668814, 2025). "SPIC and MAFB were predominantly expressed in normal and adjacent tissues, while SPP1+ TAM-associated TFs (SREBF1, JUN, SPI1, and CREB1) showed peak expression in tumor core regions." (PMID 40725473, 2025). "First, the exact mechanisms by which SREBF1 influences tumor proliferation and immune evasion remain to be fully elucidated." (PMID 40668814, 2025). "Our pan-cancer analysis revealed that SREBF1 expression exhibits tumor-type-specific correlations with immune infiltration." (PMID 40668814, 2025). "Further functional annotation can elucidate the impact of SREBF1 expression on the functions of tumor cell subsets, such as proliferation and migration." (PMID 40668814, 2025). "Although the tumor volume did not exhibit a significant reduction in the NI-57-treated group, IHC results indicated a notable decrease in SREBF1 expression within the tumor tissues following iBRD1 treatment." (PMID 39962068, 2025). "We verified the expression of SREBF1 in human colorectal cell lines, including both normal and tumor cells." (PMID 40668814, 2025). "As a transcription factor, SREBF1 plays a vital role in maintaining lipid homeostasis, which is not only significant for metabolic processes but also holds importance in tumor growth regulation." (PMID 39953634, 2025). "Serving as a fundamental transcription factor that facilitates de novo fatty acid synthesis, SREBP1, encoded by SREBF1, enhances fatty acid synthesis in tumor cells by upregulating pivotal enzymes associated with lipogenesis, such as ACC1, FASN, and SCD1." (PMID 39169280, 2024). "Knockdown of SREBF1 slowed growth of human PDAC cells in culture and in subcutaneous xenografts, however, targeting SREBF1 resulted in incomplete inhibition of cell and tumor growth." (PMID 39240063, 2024). "Considering the clinical importance of high rates of lipogenesis in rapidly proliferating cancer cell, SREBF1 was postulated to be an important molecular target to suppress tumor cell growth and activity." (PMID 37296155, 2023).
tumor (continued). "PARP inhibitors have been shown to improve both anti- and pro-tumor features of macrophages by reprogramming glucose and lipid metabolism via the sterol regulatory element-binding protein 1 (SREBF1, SREBP1) pathway." (PMID 36678877, 2023). "We, therefore, used the same AAV-based CRISPR/Cas9 strategy to target Srebf1 or Srebf2 in KPL tumours (KPLS1 and KPLS2)." (PMID 37202505, 2023). "SREBF1 expressing C4-2B formed robust tumor growth reaching ~1300 mm3 in 9 weeks, in contrast, Y673/951A double mutant expressing cells exhibited severely compromised tumors growth." (PMID 37296155, 2023). "High SREBF1 expression was significantly positively correlated with tumor size (p = 0.005), lymph node metastasis (p = 0.003), and distant metastasis (p = 0.000)." (PMID 36694250, 2023). "In our study, we identified a series of potential tumor antigens, including SREBF1, LUC7L3, LAMA5, PCGF3, HNRNPH1, KLC4, and OFD1, by systematically analyzing alternative splicing and mutation of genes in patients with HNSCC." (PMID 36467412, 2022). "In general, SREBF1 expression was more spread over a wide area in tumor samples compared to normal lung tissues." (PMID 36139614, 2022). "SREBF1 is a key enzyme for cholesterol and fatty-acid synthesis, and an essential gene for OC tumor growth." (PMID 35563265, 2022). "Sterol regulatory element-binding factors (SREBFs) are key regulators of lipid homeostasis, and specifically, the upregulation of SREBF1 gene seems to trigger LD accumulation and tumor growth." (PMID 36139614, 2022). "The yarrow supercritical extract inhibits tumor growth in PC transplantation mice models by downmodulating SREBF1 and its downstream targets, SCD and FASN." (PMID 36699061, 2022). "Analysis of RNA-seq data from the CH cohort validated that SREBF1 was associated with FASN, and was differentially expressed in normal and tumor tissues." (PMID 35392075, 2022). "The levels of Lipe, a regulator of lipolysis, as well as of Plin1 and Srebf1, involved in the control of lipid metabolism, were unchanged in the tumor hosts." (PMID 35392166, 2022). "For this, 292 patient samples (tumor and corresponding normal lung tissues from the same patient) were analyzed for the SREBF1 expression." (PMID 36139614, 2022). "SREBF1 is a vital transcription factor and promotes tumor proliferation, invasion and migration by providing the membrane building materials to support the rapid proliferation of cancer cells." (PMID 33939316, 2021). "TN stage correlation analysis demonstrated BGN, GRK5 and SREBF1 were closely correlated tumor progression." (PMID 34116604, 2021). "Regression analysis identified SREBF1 as an independent survival predictor in a multivariable model comprising the clinical tumor-node-metastasis (TNM) parameters (HR = 2.24, 95% CI = 1.36–3.71, P = 0.002)." (PMID 34272396, 2021). "Most of these genes, including SREBF1, CALM1, PCBP1, COTL1 and BTK, are tumor-related genes, which have been reported to be associated with tumorigenesis, progression and therapy." (PMID 32832275, 2020). "In two tumor samples SREBF1 had two different 5ʹ fusion partners each and three samples contained three." (PMID 28983113, 2017). "Rapamycin treatment of cultured human adipocytes resulted in down-regulation of gene expression of SREBF1 suggesting that the tumor promoting effects of the FBXW7-SREBF axis is dependent on mTOR." (PMID 26575021, 2015). "Additionally, IHC results revealed a decrease in the expression of proteins associated with fatty acid synthesis, such as SREBF1 and FASN, in tumor tissues after treatment with either CTD or RG3." (PMID 41501793, 2026). "Thus, MIAT-induced SREBF1 overexpression can largely facilitate tumor survival and development of chemoresistance." (PMID 40781643, 2025). "Moreover, there are significant differences in the level of SREBF1 methylation between normal tissues and tumor tissues." (PMID 40668814, 2025).